IL1B (interleukin 1 beta)
Diseases named in the same sentence as IL1B in open-access papers (continued):
Sharing a sentence is not in itself a finding about the gene and the disease.
Cerebral ischemia (continued). "Gene expression of TNF-α and IL-1β, after cerebral ischemia is up-regulated." (PMID 23351182, 2012). "Syringin reduces the expression of inflammatory factors(interleukin (IL)‐1β, tumor necrosis factor‐α, and IL‐6), and neutrophil infiltration and increases forkhead box O3A phosphorylation, thereby inhibiting nuclear factor kappa B expression and protecting against cerebral ischemia." (PMID 40566933, 2025). "In models of cerebral ischemia, astrocytes exhibit a neuroprotective subtype, whereas under neuroinflammatory conditions, inflammatory microglia are able to induce astrocyte activation into a neurotoxic subtype by secreting three factors, IL‐1β, TNF‐α, and C1q." (PMID 39508266, 2024). "Thus, the increased IL-1β and IL-6 in the blood may contribute to the worsened neurological outcome with aging after brain ischemia." (PMID 37697393, 2023). "To further investigate whether MFSCE attenuates neuroinflammation after cerebral ischemia, we determined the expression of NLRP inflammasome-associated proteins, including NLRP1, NLRP3, ASC, CL-caspase-1, CL-caspase-11, IL-1β, and IL-18 in the ischemic cortex using Western blotting." (PMID 35454994, 2022). "This treatment reduced the expression of NLRP3, caspase-1, and IL-1β, and the occurrence of cell pyroptosis and inflammatory response, suggesting that the protective effect of EA on cerebral ischemia/reperfusion injury may be played by inhibiting the pyroptosis pathway dependent on caspase-1." (PMID 35600074, 2022). "Therefore, the cerebral ischemia increases MCP‐1 expression in endothelial cells and/or neurons, which causes the activation of microglia, leading to inflammatory response such as increases in IL‐1β and TNF‐α expression, and VCI in small vessel disease." (PMID 34586752, 2021). "The peak expression of IL-1β mRNA was at 16 h, and it was then downregulated, suggesting that IL-18 may have a certain degree of regulation on the inflammatory response in the late stage of cerebral ischemia." (PMID 32194375, 2020). "Likewise, previous study manifests that apelin-13 exerts a protective role for neurons against cerebral ischemia/reperfusion (I/R) injury through inhibiting the expression of inflammatory factors (IL-1β, TNF-α, and ICAM-I) and the activation of microglia and astrocytes." (PMID 31040784, 2019). "Furthermore, we found that the mRNA transcription levels of NLRP3, IL-1β, and caspase-1 in the core ischemic area were remarkably amplified in diabetic mice with cerebral ischemia-reperfusion injury, whereas this phenomenon was obviously attenuated by MCC950 pretreatment." (PMID 29853850, 2018). "Following cerebral ischemia/reperfusion, the NLRP3 inflammasome is rapidly activated within microglia, serving as a primary source of inflammatory mediators such as IL-1β." (PMID 41383474, 2025). "Activation of NF-κB induces the production of pro-inflammatory cytokines (IL-4, IL-10, IL-13, TGF-β) and adhesion molecules (IL-6, IL-1β and ICAM-1), thus intensifying tissue injury in cerebral ischemia-reperfusion." (PMID 40656619, 2025). "It dramatically lowers glial cell activation, neuronal mortality, and the release of inflammatory markers (including IL-1β, TNF-α, and IL-6) in the cerebral ischemia-reperfusion paradigm." (PMID 41383474, 2025). "Microglia and astrocytes are activated within minutes after cerebral ischemia and release some pro-inflammatory factors, such as TNF-α, NF-κB, IL-1β, and IL-6." (PMID 41329542, 2025). "Cerebral ischemia triggers diffusion impairment of the blood-brain barrier, concomitant with an accumulation of pro-inflammatory mediators (TNF-α, IL-1β, IL-6) within the brain and serum, provoking an inflammatory cascade." (PMID 40144659, 2025). "In a study of blood mononuclear cells from patients with cerebral ischemia, increased expression of circRNA HECTD1 in these cells was demonstrated, which correlated with blood levels of TNF-α, IL-6, and IL-1β." (PMID 41245147, 2025).
Cerebral ischemia (continued). "Brain ischemia induced significant elevations in plasma levels of the pro-inflammatory TNF-α, IL-6, and IL-1β, which were significantly mitigated by 3-MP." (PMID 40095189, 2025). "During cerebral ischemia, the expression of both pro-inflammatory, as TNF-α, IL-1β, IL-6, and anti-inflammatory cytokines, MCPIP1, rapidly increases throughout the brain tissue." (PMID 37812268, 2024). "In the acute phase of cerebral ischemia, the proliferation and activation of microglia led to a robust inflammatory response, characterized by increased levels of TNF and IL-1β and upregulation of IL-6, which can result in sleep disorders." (PMID 38671959, 2024). "Cerebral ischemia induced a transient increase of TNF, IL-1β, IL-6, CXCL1, and CCL5 at day 1 post-pMCAO, corresponding to the peak of pro-inflammatory cytokines typically observed in this model." (PMID 38142915, 2024). "Microglial cells, the resident macrophages of the brain, are activated within minutes after the onset of cerebral ischemia and release proinflammatory agents such as tumor necrosis factor alpha (TNF-α) or interleukin-1 beta (IL-1β)." (PMID 37958527, 2023). "In summary, our results revealed that cerebral ischemia induced the upregulation of ROS and NLRP3, Caspase-1, and IL-1β expression, whereas HS reduced the levels of all these factors." (PMID 37371417, 2023). "Cerebral ischemia produces great amounts of proinflammatory factors such as TNF-α and IL-1β and inhibits the production of anti-inflammatory factors such as IL-10 and IL-449." (PMID 37132753, 2023). "After cerebral ischemia, the NF-κB pathway extends the inflammatory response in the brain, activating inflammatory signals such as iNOS, COX-2, IL-1β, TNF-α, IL-6, and others." (PMID 35838888, 2023). "The results of our study revealed that after cerebral ischemia, there is a significant increase in NDS, cerebral edema, and infarct volume, and TLR4, p‐p38MAPK, p‐JNK, and IL‐1β expression were all upregulated in the initial phase after tMCAO." (PMID 37904689, 2023). "In the cerebral ischemia-reperfusion model used to study it, SYR, like other compounds, reduced the expression of NF-κB, IL-1β, IL-6, and TNF-α." (PMID 38813032, 2023). "RvD1 ameliorated neuronal death, decreased IL1β, TNFα, malondialdehyde, MDA, and NLRP3 protein in rats with cerebral ischemia/reperfusion injury." (PMID 36670960, 2022). "The ELISA results showed that the levels of IL-1β, IL-6, and TNF-α were abnormally increased in the serum of rats with cerebral ischemia." (PMID 35467483, 2022). "The M1 type microglia excretes a large number of inflammatory factors such as IL-6, IL-1β, IL-12 and TNF-α, which aggravate cerebral ischemia/reperfusion injury." (PMID 35658867, 2022). "After cerebral ischemia, the changes in the intracellular microenvironment trigger the NLRP3 inflammasome (NLRP3/ASC/CASPASE-1) activation, which leads to the secretion of IL-1β and IL-18 and finally mediated cell death." (PMID 36091745, 2022). "Brain ischemia significantly upregulated mRNA expression of TNF‐α, IL‐1β, and IL‐6, which were inhibited by BMPER." (PMID 34904361, 2022). "In the study of cerebral ischemia-reperfusion injury, the expression of TNF-α, IL-1β, and IL-6 was significantly decreased after Acacetin treatment compared with the middle cerebral artery occlusion group." (PMID 34594156, 2021). "For example, α-pinene was able to attenuate neuro-inflammation in a rat model of focal cerebral ischemia-reperfusion by decreasing both the gene and protein expression of TNF-α and IL-1β." (PMID 35145398, 2021). "It has been accepted that berberine can decrease inflammatory agents-induced IL-1B and TNF-a ensuing inflammation in cerebral ischemia." (PMID 34600570, 2021). "Second, we compared the effect of BBR and BBR-loaded micelle on TNF-a, IL-1B (inflammations factors), and MDA (marker of oxidative stress) due to inducing cerebral ischemia in the rat." (PMID 34600570, 2021).
Cerebral ischemia (continued). "After cerebral ischemia-reperfusion, inflammatory cell activation is followed by the release of proinflammatory factors such as TNF-α and IL-1β." (PMID 34853620, 2021). "In cerebral ischemia, NLRP3 inflammasome activation evoked the cleavage of caspase-1, thereby cleaving GSDMD, pro-IL-1β, and pro-IL-18 to GSDMD-N, mature IL-1β, and IL-18, respectively." (PMID 34630845, 2021). "In animal studies of global brain ischemia, VPA further suppressed IL-1β production in the hippocampus." (PMID 34122007, 2021). "Proinflammatory pathways that are activated due to brain ischemia-reperfusion are characterized by TNF-α and interleukin-1β (IL-1β) synthesis." (PMID 33953854, 2021). "In the striatum, we have shown that relative expression of Nt‐3, Nestin, β‐actin, Tnfα, Il‐1β, Il‐6, and Il‐10 increased whereas expression of Bdnf, Gdnf, Vegf, and β‐III tubulin decreased after cerebral ischemia." (PMID 32281225, 2020). "Electroacupuncture can effectively decrease the expression of NF-κB p65, IL-1β, and TNF-α after cerebral ischemia and inhibit the conversion of microglia to the M1 phenotype after ischemic brain injury." (PMID 32922507, 2020). "During cerebral ischemia, activated microglial cells migrate to inflammatory sites and produce excessive neurotoxic and inflammatory mediators, such as TNF-α, IL-1β, IL-6, MCP-1, MIP-1, PGE2 and NO, which exacerbate neuronal damage." (PMID 33373319, 2020). "Electroacupuncture alleviates cerebral inflammation in cerebral ischemia/reperfusion injury through the TLR4/NF-κB pathway, which is accompanied with the suppressed secretion of the inflammatory cytokines TNF-α, IL-1β and IL-6." (PMID 32479555, 2020). "The studies reported that the activation of the NLRP3 inflammasome leads to the development and release of inflammatory cytokines IL-1β and IL-18, suggesting the role for the NLRP3 inflammasome in the initiation and development of cerebral ischemia." (PMID 32153398, 2020). "The increase of IL-1β enhances TNF-α level in a synergistic way and these inflammatory cytokines promote the neuroinflammation process and brain ischemia damage." (PMID 32963745, 2020). "Dexmedetomidine pretreatment attenuated neurological injury, brain lesions and expression of inflammatory factors (IL-1β, IL-6, TNF-α) after brain ischemia (P < 0.05)." (PMID 33287729, 2020). "Indeed, no matter whether the target is upstream or downstream in the NLRP3 inflammasome pathway at the molecular level, modulating the expression, assembly, activation and secretion of the NLRP3 inflammasome and IL-1β exerts a protective effect on cerebral ischemia-reperfusion injury." (PMID 31747940, 2019). "To provide evidence of MCC950 to the protective effect of cerebral ischemia reperfusion in diabetic mice, we measured the mRNA levels of NLRP3, IL-1β, and caspase-1 in the boundary zone adjacent to the ischemic core." (PMID 29853850, 2018). "The activation of TLR-4 activates NF-κB during cerebral ischemia, and NF-κB further promotes the production of NLRP3 and IL-1β— thus, enhancing inflammation." (PMID 30618576, 2018). "Among them, TNF-α, IL-1β and IL-6, iNOS and COX-2 are all dynamically altered in different stages of brain ischemia-reperfusion, and they usually bring detrimental effect to brain and BBB." (PMID 30622459, 2018). "IL-1β also has a synergistic effect with TNF-α to further exacerbate brain damage and cerebral ischemia can upregulate TNF-α and participate in the pathological process of brain injury, while TNF-α can promote the release of IL-1β and other cytokines." (PMID 28491108, 2017). "Here, these pro-inflammatory cytokines (IL-1β, IL-6, and TNF-α) were chosen as markers to evaluate the inhibition of the inflammatory response at 24 h after cerebral ischemia and reperfusion in the hippocampus." (PMID 28769792, 2017). "Our results showed that cerebral ischemia induced upregulation of IL-6, TNF-α, and IL-1β significantly, when compared with that of the control group." (PMID 28855861, 2017).
Cerebral ischemia (continued). "TCMs effectively ameliorate cerebral I/R injury by downregulating TLR4, TNF-α, IL-1β, IL-6, iNOS, COX-2, and 5-LO expression and upregulating IL-10 expression in the ischemic area during the acute and subacute phases of cerebral ischemia." (PMID 27703487, 2016). "The anti-inflammatory properties of FBD can be further attributed to IL-1β, TNF-α, and IL-8 downregulation during the acute phase of cerebral ischemia." (PMID 27703487, 2016). "During cerebral ischemia, proinflammatory mediators such as TNF-α, IL-1β, and IL-6 are excessively produced by a variety of activated cell types, including microglia, endothelial cells, astrocytes, and neuron cells, which finally exacerbated neuronal injury." (PMID 27123035, 2016). "It is involved in the regulation of inflammation and its activation is correlated with significant increases in levels of IL-1β and TNF-α following cerebral ischemia-reperfusion." (PMID 25815894, 2015). "During brain ischemia, proinflammatory cytokines such as TNF-α, IL-1β, IL-6, and chemokines such as CINC and MCP-1 are produced by a variety of activated cell types, including endothelial cells, microglia, astrocytes, and neurons." (PMID 25888869, 2015). "Induction of cerebral ischemia increased the TNF-α, IL-6 and IL-1β mRNA expression levels significantly at 4 and 24 h in the left ischemic hemispheres in the hypoxia group compared with those in the control group." (PMID 24520277, 2014). "Meanwhile, as target genes of NF-κB, several pro-inflammatory cytokines and enzymes, such as TNF-α, IL-1β and cyclooxygenase (COX)-2 are upregulated and lead to neuronal damage after cerebral ischemia." (PMID 23997755, 2013). "First, it has been reported that cerebral ischemia also induces activation of astrocytes, another resident cells in the brain, which can produce the proinflammatory cytokines including TNF-α, IL-1β and IL-6." (PMID 24349350, 2013). "Accordingly, TNFα, IL-6 and IL-1β have been shown to correlate to the severity of SAH, cerebral vasospasm, development of late cerebral ischemia and secondary brain damage in primate." (PMID 23259581, 2012). "Moreover, after reversible experimental local cerebral ischemia, lncRNA H19 was shown to promote leukocyte activation via the miRNA-29b/C1QTNF6 axis, triggering the release of TNF-α and IL-1β, which enhanced neuroinflammation." (PMID 41245147, 2025). "An animal experiment illustrated that anti-CD147 antibody could inhibit the inflammatory response of monocyte/macrophage in the spleen after cerebral ischemia in mice and reduce the levels of TNF-α, IL-6 and IL-1β in the spleen." (PMID 38932932, 2024). "Furthermore, IL-1β, IL-6 and TNF-α mRNA levels were enhanced after cerebral ischemia‒reperfusion injury, consistent with previous reports." (PMID 37248543, 2023). "In addition, we investigated the anti‐inflammatory properties of Sal B. Following cerebral ischemia, we found that Sal B significantly reduced TLR4, p‐p38MAPK, p‐JNK, IL‐1β expression, and nuclear translocation of NF‐κB." (PMID 37904689, 2023). "In our study, the results demonstrated that the number of TUNEL-positive cells, Bax, cleaved caspase-3, cleaved caspase-9, PARP, IL-1β, IL-6 and TNF-α protein expression were enhanced after cerebral ischemia‒reperfusion injury, while antiapoptotic Bcl-2 protein expression was decreased." (PMID 37248543, 2023). "Concurrently, the anti-inflammatory property of CEP enables its use in the treatment of cerebral ischemia/reperfusion injury, wherein CEP inhibits NLRP3 signaling, and caspase-1, thereby suppressing the overproduction of IL-1β and IL-18, thus attenuating cerebral ischemia/reperfusion injury." (PMID 36677811, 2023). "Cerebral ischemia also resulted in a significant increase of protein levels of the adaptor protein ASC, activated Caspase-1, and the cleavage product of inflammasomes, IL-1β (p < 0.05)." (PMID 34628598, 2022).
Cerebral ischemia (continued). "Double immunofluorescence staining for NeuN/Caspase1, NeuN/GSDMD, NeuN/IL-1β, MAP2/ASC, MAP2/GSDMD and NLRP1/GSDMD further confirmed that iTBS post-treatment is capable of inhibiting cerebral ischemia-induced pyroptosis of neuron in peri-infarcted area rather than at the border of infarcted core." (PMID 35690810, 2022). "Neutrophils are involved in brain injury after cerebral ischemia by releasing proteases, including elastase, metalloproteinase (MMP9) and cathepsin G, as well as reactive oxygen species, nitrogen species and inflammatory IL-1β." (PMID 36818726, 2022). "Our results showed that Tanshinone IIA could inhibit the expression of pro-inflammatory factors TNF-α, IL-6, and IL-1β and regulate the levels of SOD and MDA in the brain tissue of rats with cerebral ischemia." (PMID 33953677, 2021). "The co-administration of PDRN and DMPX failed to decrease TNF-α and IL-1β expressions observed with PDRN in cerebral ischemia." (PMID 33735236, 2021). "At the early stage of cerebral ischemia, the activation of glial cells and infiltration of leukocytes in the injured tissue produced great amounts of pro-inflammatory factors such as TNF-α and IL-1β, contributing to BBB damage and hemorrhagic transformation." (PMID 32508671, 2020). "Cerebral ischemia may damage cell membranes of neurons and glial-cells, leading to the release of TNF-α, IL-1β, and IL-6." (PMID 32848589, 2020). "Two hours after cerebral ischemia, the expression levels of TNF-α and IL-1β were increased." (PMID 32922507, 2020). "Results of the present study showed that cerebral ischemia and reperfusion could trigger inflammatory responses that manifested in increasing pro-inflammatory cytokines such as TNF-α and IL-1β." (PMID 32742603, 2020). "Moreover, our results clearly demonstrate that PEA-OXA treatment downregulated the IL-1β, TGF-β, and TNF-α expression induced by cerebral ischemia." (PMID 31569558, 2019). "Previous studies have demonstrated that Andro could decrease the production of cytokines including TNF-α and IL-1β, and pro-inflammatory factors such as PGE2 through inhibiting NF-κB activation to protect against cerebral ischemia." (PMID 30294256, 2018). "Inflammatory responses (such as the release of proinflammatory cytokines interleukin-1 β (IL-1β), IL-6, and tumor necrosis factor (TNF-α)) increase the expression of adhesion molecules in white blood cells and vascular endothelial cells after brain ischemia and reperfusion." (PMID 29540536, 2018). "Furthermore, curcumin (200 mg/kg) attenuates inflammation by decreasing inflammatory mediators, such as interleukin-1 beta (IL-1β), tumor necrosis factor-alpha (TNF-α), Prostaglandin E2 (PGE2), NO, COX-2, and iNOS, induced by brain ischemia in rats." (PMID 29220411, 2017). "The results of the present study indicated that paeonol pretreatment can reduce cerebral infarction volume; neurological deficits; TLR2-, TLR4-, Iba1-, NF-κB-, and IL-1β-immunoreactive cell numbers; and TUNEL-positive cells in cerebral ischemia-reperfusion injured rats." (PMID 28101118, 2016). "In addition, curcumin suppressed neuroinflammatory response by decreasing inflammatory mediators, such as IL-1β, TNF-α, PGE2, NO, COX-2, and iNOS induced by cerebral ischemia of rats." (PMID 23762140, 2013). "Results showed that sevoflurane postconditioning can decrease serum tumor necrosis factor-alpha (TNF-α), interleukin-1 beta (IL-1β), nitric oxide (NO), nitric oxide synthase (NOS) and increase serum interleukin-10 (IL-10) levels in cerebral ischemia reperfusion rats." (PMID 22210172, 2011). "TNFα, IL-1β, IL-6 and MCP-1 expression was substantially upregulated after brain ischemia." (PMID 22196138, 2011). "Therefore, inhibiting the release of IL1β, IL6, and TNFα can effectively reduce neuron apoptosis, improve neurological deficits, reduce the disability rate and improve the quality of life of patients with cerebral ischemia." (PMID 41154631, 2025).